XIAP (X-linked inhibitor of apoptosis)
Diseases named in the same sentence as XIAP in open-access papers (continued):
Sharing a sentence is not in itself a finding about the gene and the disease.
melanoma (continued). "IAP family members include survivin, inhibitors of apoptosis (c-IAP1 and c-IAP2), X-linked inhibitor of apoptosis (XIAP), BIR-repeat-containing ubiquitin-conjugating enzyme (BRUCE/Apollon), IAP-like protein 2 (ILP-2), neuronal apoptosis inhibitor protein (NAIP) and melanoma IAP (ML-IAP/Livin)." (PMID 36185861, 2022). "Moreover, the inhibition of imiquimod‐induced ROS accumulation by NAC or NF‐κB pathway by its specific inhibitor (Bay11‐7082) blocked imiquimod‐induced activation of NF‐κB and subsequently the expression of apoptosis inhibitor XIAP, and enhanced the apoptosis of melanoma." (PMID 26578344, 2016). "Preclinical data in melanoma mouse xenografts and osteosarcoma cells, showed that dinaciclib induces apoptosis, increases Bax and Bim in mitochondria, and decease antiapoptotic factors, such as Mcl-1, Bcl-2, Bcl-xL and XIAP, as well as phosphorylation of Ser2 of RNA Pol II." (PMID 25596730, 2015). "TRI-03 also reduces XIAP expression via the autophagy pathway, facilitating caspase activation and resulting in irreversible GSDME-mediated pyroptosis in melanoma cells." (PMID 40486906, 2025). "We discovered that both compounds partially suppressed cell death and LDH release in response to TRI-03 treatment in melanoma cells, indicating that TRI-03-induced pyroptosis depends at least partially on autophagy-mediated XIAP degradation." (PMID 40486906, 2025). "ADA inhibits the PI3K/Akt pathway and its downstream target NF-κB in melanoma cells, reduces the expression of the anti-apoptotic proteins c-FLIP, XIAP and Bcl-2, and promotes the activation of caspase-3 and PARP to induce apoptosis." (PMID 38448410, 2024). "The small-molecule ARTS mimetics can degrade XIAP and induce apoptosis, as shown by its ability to promote caspase-3 cleavage and PARP cleavage in A375 melanoma and in T-ALL Jurkat cell lines." (PMID 32182843, 2020). "In melanoma cells, intrinsic TRAIL resistance was correlated with the expression of caspase antagonists such as elevated expression of XIAP, survivin, and c-FLIP." (PMID 31083589, 2019). "Taken together these results indicate that effectiveness of combination treatment on melanoma cells is due to an induction of BIM and a simultaneous decrease in expression of anti-apoptotic proteins Bcl-2, Bcl-XL and XIAP." (PMID 26087189, 2015). "In melanoma, HDAC inhibitors inhibit expression of anti-apoptotic proteins survivin, Bcl-XL, Bcl-2, Mcl-1, XIAP, mostly via decreased transcription." (PMID 26426052, 2015). "Treatment of two melanoma cell lines (Me13 and Me41) with the AZD6244–BEZ235–TRAIL combination induced strong downmodulation of c-IAP1, c-IAP2, XIAP and Apollon compared with the effects of single agents and to AZD6244–BEZ235 treatment." (PMID 25275595, 2014). "Although clinical toxicity data using the XIAP targeting drug AEG 35156 are pending, we believe that the approach of targeting XIAP in order to sensitize melanoma cells to chemotherapy is worthy of further investigation." (PMID 17257402, 2007). "XIAP ubiquitinates RIPK2 and recruits neutrophils to inhibit growth of melanoma." (PMID 40133252, 2025). "Consequently, future research on autophagy-mediated XIAP degradation may not only identify and validate key molecules and signaling pathways involved in selective autophagy but also facilitate the development of new drugs in melanoma therapy and interventions to enhance autophagy capabilities." (PMID 40486906, 2025). "Mechanistically, TRI-03 not only increases intracellular reactive oxygen species (ROS) levels by inhibiting TrxR1 activity but also decreases XIAP expression, leading to the activation of the caspase-9/caspase-3/GSDME axis and irreversible GSDME-mediated pyroptosis in melanoma cells." (PMID 40486906, 2025). "PTX significantly augmented IL-6 and IL-8 expressions in MDA-MB-231 BCA and in MDA-MB-435 melanoma cells whereas XIAP mRNA was also induced by PTX but was not statistically significant." (PMID 29486738, 2018).
melanoma (continued). "This supports the findings herein that XIAP was up-regulated in PTX-treated BCA and melanoma cells." (PMID 29486738, 2018). "In addition, CpdA dramatically attenuated TLR4-induced IL-6, IL-8 and XIAP expressions in both MDA-MB-231 BCA and MDA-MB-435 melanoma cells compared to cells with only PTX treatment." (PMID 29486738, 2018). "Our analysis of a large number of cultured melanoma cells identified largely uniform expression of XIAP and cIAP1, but not of cIAP2." (PMID 26355347, 2015). "Subsequent work on melanoma confirmed this result, and also showed that MBZ decreased the levels of X-linked inhibitor of apoptosis (XIAP), but to date this has not been confirmed in non-melanoma cell lines." (PMID 25075217, 2014). "The exogenous H2S donor, NaHS, amplifies the apoptotic process in melanoma A375 and SK-MEL-282 cells, demonstrating the antitumor effect of H2S treatment at high concentrations (via suppression of the PI3K/AKT/mTOR, NF-KB, AKT, ERK1/2, MAPK/ERK, PI3K/Akt pathways, FLIP, XIAP, Bcl-2, PHLDA genes)." (PMID 41373571, 2025). "An earlier study revealed that knockdown of Bcl-2 in TRAIL-resistant melanoma cells could make these cells sensitive to TRAIL although the effect was not as potent as that of XIAP knockdown." (PMID 34299249, 2021). "Finally, overexpression of XIAP protected melanoma cells from apoptosis induced by TRAIL and combinations, whereas its siRNA-mediated knockdown could sensitize melanoma cells for TRAIL." (PMID 31083589, 2019). "To investigate whether XIAP expression level might serve as a biomarker predicting responsiveness to TRAIL receptor-activating agonistic molecules in general, we correlated semi-quantitative XIAP protein expression level with IZI1551 responsiveness in five different mutBRAF melanoma cell lines." (PMID 30416750, 2018). "Taken together, the interplay of caspases-3, XIAP and Bcl-2 family members, initiated by non-limiting amounts of TRAIL receptors and caspase-8, appears to play a central role in melanoma cell death upon exposure to IZI1551/Birinapant." (PMID 32081986, 2020).
prostate carcinoma (77 papers, 2006 to 2026). A carcinoma that arises from epithelial cells of the prostate gland. "circ0005276 interacted with FUS to activate the transcription of its host gene XIAP (X-linked inhibitor of apoptosis protein) to regulate the process of prostate cancer." (PMID 35733138, 2022). "Examples include circ0005276 in prostate cancer cells through the activation of X-linked inhibitor of apoptosis protein (XIAP) and circVAPA in HCC cells through the activation of prosaposin (PSAP)." (PMID 34162394, 2021). "The transcription factor RUNX2 can prevent prostate cancer cell apoptosis, and inhibition of X-linked inhibitor of apoptosis (XIAP) is being studied as a strategy to enhance apoptosis and prevent cancer cell proliferation." (PMID 26504486, 2015). "In the current report, we demonstrate for the first time that cadmium down-regulates expression of the X-linked inhibitor of apoptosis protein (XIAP) in prostate cancer cells." (PMID 20618956, 2010). "In addition, lncRNA SBF2-AS1 in TAM exosomes promoted the expression of the X-linked inhibitor of apoptosis protein (XIAP) and tumor progression in prostate cancer cells." (PMID 37048103, 2023). "Indeed, XIAP deficiency can result in more aggressive disease in a murine prostate cancer model which suggests a degree of caution to be employed before XIAP antagonists are used for cancer therapy." (PMID 35562367, 2022). "We suggest that the loss of XIAP we observed in prostate cancer cells treated with the drug combination might contribute to their increased apoptotic response compared to the individual drug applications." (PMID 29182622, 2017). "Another pathway positively associated with XIAP levels in prostate cancer is AKT." (PMID 25686839, 2015). "In addition, quercetin in combination with epigallocatechin gallate inhibits the invasion and progression of prostate cancer stem cells via activation of X-linked inhibitor of apoptosis protein (XIAP) and survivin, leading to its metastasis inhibition potential in prostate cancer." (PMID 33807174, 2021). "Our results indicate that alterations in the expression of IAPs and caspases contribute to the malignant behavior of prostate tumors and suggest that tumor expression of XIAP, procaspase-3 and cleaved caspase-3 may help to identify prostate cancer patients at risk of progression." (PMID 26507126, 2015). "The mechanism is that circ‐XIAP can directly target miR‐1182 and subsequently promote multidrug resistance in prostate cancer by regulating the miR‐1182/TPD52 axis, which is a promising therapeutic target for prostate cancer chemotherapy." (PMID 39239069, 2024). "The circRNA X-linked inhibitor of apoptosis (circ-XIAP) is derived from the mRNA back-splicing of the XIAP gene, which serves as an oncogene in prostate cancer (PCa)." (PMID 36594094, 2023). "The expression of three genes (BCL2L11, PIK3CA, and XIAP) regulated in opposite directions (up/down) occurred in patients with HD and breast/prostate cancer." (PMID 37298337, 2023). "PC3 overexpress the anti-apoptotic protein XIAP, as many prostate cancer cells do, thus reducing their propensity to undergo apoptosis." (PMID 35163077, 2022). "Increasing evidence suggests that suppression of XIAP can inhibit tumor growth in gastric cancer, prostate cancer, colon cancer, and HCC." (PMID 35484994, 2022). "circ0005276 can positively target X-linked inhibitor of apoptosis protein (XIAP), enhance EMT, and induce prostate cancer progression." (PMID 35984196, 2022). "Both XIAP and circ0005276 show the highest expression in prostate cancer patients compared to healthy individuals." (PMID 34449657, 2021).
prostate carcinoma (continued). "In sum, upregulation of circ0005276 in prostate cancer promotes expression of XIAP, which induces proteasomal degradation of MDM2, leading to inhibition of autophagy and an increase in cancer progression." (PMID 34449657, 2021). "It was proven that XIAP played a fundamental role in the resistance of anoikis and cancer metastasis in prostate cancer." (PMID 34712428, 2021). "A recent study suggested that PIM-2 cooperates with downstream factor XIAP, and thus inhibits the apoptosis of prostate cancer cells." (PMID 32062612, 2020). "circRNA0005276 promoted XIAP transcription and facilitated proliferation and migration of prostate cancer cells." (PMID 33138314, 2020). "Mechanistically, to promote prostate cancer growth, YY1 has been shown to repress the expression of X-linked inhibitor of apoptosis (XIAP) associated factor-1 (XAF1), a tumor suppressor in prostate cancer cells." (PMID 31824839, 2019). "Embelin was previously identified as a small molecular inhibitor of the X-linked inhibitor of apoptosis proteins that can cause cell death through activating caspase-9 and subsequent cell apoptosis in prostate cancer cells with high levels of XIAP." (PMID 31635287, 2019). "XIAP’s function as a metastatic driver by its activation of the NFκB pathway via E3 Ligase activity in human prostate cancer cells." (PMID 31240993, 2019). "XIAP functions as a metastatic driver by activation of the NFκB pathway viaitsE3 ligase activity in human prostate cancer cells." (PMID 31240993, 2019). "Exposure of prostate cancer cells to the PEITC reduces suppression of Bcl-2 and X-linked inhibitor of apoptosis protein (XIAP) levels and induction of Bax and Bak." (PMID 30445746, 2018). "This adds significance to a previous study evaluating the prognostic capability of XIAP in prostate cancer and others indicating an anti-tumor role for this IAP." (PMID 26507126, 2015). "Our data provides evidence that PN1 can regulate signalling by neutralising complexes uPA-uPAR and altering downstream pathways that contribute to the transcriptional activation and stabilization of the survival factor XIAP in prostate cancer cells." (PMID 25686839, 2015). "Here, we show evidence that an endogenous serine protease inhibitor, protease nexin-1 (PN1), leads to reduced expression of XIAP, resulting in induction of apoptosis in prostate cancer." (PMID 25686839, 2015). "Here we show co-expression of p65 and XIAP in the more advanced prostate cancers (Gleason 8–10), and that PN1 protein is concurrently decreased." (PMID 25686839, 2015). "Elevated XIAP expression was observed in prostate cancer and poor prognostic factors; however, statistical significance was not reached." (PMID 25071009, 2014). "Of the IAP family members, cIAP1, cIAP2, XIAP and survivin are known to be up-regulated in prostate cancer." (PMID 25071009, 2014). "Four IAP members, i.e. XIAP, survivin, cIAP1 and cIAP2, have been reported to be up-regulated in prostate cancer." (PMID 25071009, 2014). "Additional early small-molecule XIAP-inhibitors such as the polyphenylurea-based antagonists 1396-12 and 1396-34 efficiently inhibited the growth of prostate cancer xenografts in mice and showed little toxicity on normal tissues." (PMID 25120954, 2014). "The combined targeting of the three IAPs c-IAP1, c-IAP2 and XIAP in prostate cancer cells decreased proliferation and sensitised cells to TRAIL treatment." (PMID 22797576, 2012). "High level expression of NAIP along with SURVIVIN, cIAP-1, cIAP-2 and XIAP were reported in prostate cancer cell line." (PMID 22357131, 2012). "In LNCaP prostate cancer cells, XIAP restrained apoptosis induced by Paclitaxel through cutting down activity of caspase-3 and inhibiting processing of pro-caspase-3 moreover." (PMID 21645409, 2011). "Recent studies demonstrate that XIAP antagonist 1396-34 sensitizes PC-3 and DU-145 prostate cancer cells to chemotherapeutic agents and TRAIL." (PMID 20618956, 2010).
prostate carcinoma (continued). "Given that XIAP contains three zinc-binding BIR domains and a zinc-binding RING domain, we examined the impact of cadmium on the expression of XIAP in prostate cancer cell lines." (PMID 20618956, 2010). "Here, we demonstrate that cadmium down-regulates the expression of XIAP at the post-transcriptional level in prostate cancer cells." (PMID 20618956, 2010). "In this study we investigated the molecular mechanisms of cadmium-mediated XIAP down-regulation in prostate cancer cells." (PMID 20618956, 2010). "In accord with these reports, our data show that cadmium-mediated down-regulation of XIAP coincides with increased sensitivity of PC-3 prostate cancer cells to TNF-α-mediated apoptosis." (PMID 20618956, 2010). "In prostate cancer, increased expression of cIAP-1, cIAP-2, XIAP and survivin have been found in biopsy specimens from all stages of the disease, suggesting an important role in development and progression." (PMID 19549337, 2009). "Nevertheless, blocking XIAP function by transient overexpression of Smac achieved a promising enhanced efficacy in combination with TRAIL in prostate cancer cell lines, indicating that XIAP is the predominant target for TRAIL sensitivity." (PMID 19895686, 2009). "cIAP-1, cIAP-2 and XIAP where knocked down either individually or in combination using siRNA in androgen independent prostate cancer PC-3 cells as confirmed by real-time PCR and western blotting." (PMID 19549337, 2009). "Circ‐XIAP was found to be overexpressed in the exosomes of docetaxel (DTX)‐resistant prostate cancer cells and could be delivered via exosomes." (PMID 39239069, 2024). "Besides, circ0005276 was found to recruit FUS to increase mRNA stability of XIAP, thereby promoting prostate cancer progression." (PMID 38012555, 2023). "Additionally, we aimed to explore the therapeutic potential of a combined treatment involving an androgen receptor antagonist (bicalutamide) and a XIAP inhibitor (embelin) to suppress prostate cancer growth." (PMID 37564213, 2023). "A recent study has shown that knockdown of the exosomal circRNA X-linked inhibitor of apoptosis (circXIAP) could restrain cell migration and proliferation, and induce cell apoptosis, leading to docetaxel (DTX) sensitization in prostate cancer cells." (PMID 36874026, 2023). "XIAP also represses apoptosis of prostate cancer cells and glioblastoma cells." (PMID 33097010, 2020). "PIM-2 inhibited apoptosis of prostate cancer cells by downstream factor XIAP." (PMID 32062612, 2020). "Additionally, TRAIL-resistant prostate cancer cells expressed excessive amounts of XIAP and cIAP and exhibited improved TRAIL sensitivity when XIAP expression was knocked down." (PMID 28424988, 2017). "In addition, EVs from African-American patients with prostate cancer contained significantly higher amounts of the IAPs Survivin (P<0.05), XIAP (P<0.001), and cIAP-2 (P<0.01) than EVs from European-American patients." (PMID 28981528, 2017). "Protein expression of caspases (procaspase-8, cleaved caspase-8, procaspase-3, cleaved caspase-3, caspase-7 and procaspase-9) and IAPs (cIAP1/2, cIAP2, NAIP, Survivin and XIAP) was analyzed by immunohistochemistry in radical prostatectomy samples from 84 prostate cancer patients." (PMID 26507126, 2015). "Antisense inhibitors of XIAP led to sensitization of castration-resistant prostate cancer cells to cisplatin and TNF-related apoptosis-inducing ligand (TRAIL); in PC3 prostate cancer xenografts, they caused sustained tumor regression in combination with docetaxel." (PMID 23409057, 2013). "Cadmium-mediated XIAP depletion occurs at the post-transcriptional level via an NF-κB-independent, proteasome-mediated mechanism and coincides with an increased sensitivity of prostate cancer cells to TNF-α-mediated apoptosis." (PMID 20618956, 2010).